DEFB113 (defensin beta 113)
Description:
Has antibacterial activity.
Synonyms: DEFB-13
Tractability: Antibody: UniProt places it where antibodies can reach, with medium confidence; UniProt predicts a signal peptide or a membrane-spanning region; its Gene Ontology location is reachable by antibodies, with medium confidence.
Gene: Protein-coding gene on chromosome 6 (49,968,677 to 49,969,625, reverse strand). Ensembl gene ENSG00000214642.
Subcellular location: Secreted
Pathways (Reactome):
Immune System: Beta defensins; Defensins
Gene Ontology:
Biological process: innate immune response
Cellular component: extracellular region
Genetic constraint (gnomAD): Loss-of-function variants: 4 observed, 1.54 expected, observed/expected ratio (o/e) 2.59. That is too few expected variants to judge how well the gene tolerates losing a copy. Missense variants: 97 observed, 72.91 expected, observed/expected ratio (o/e) 1.33, 90% interval 1.13 to 1.58. Synonymous variants: 33 observed, 23.23 expected, observed/expected ratio (o/e) 1.42, 90% interval 1.07 to 1.84.
Homologues: Orthologues: chimpanzee DEFB113 (95% identical), macaque DEFB113 (84% identical), guinea pig DEFB113 (68% identical), dog DEFB113 (67% identical), pig DEFB113 (62% identical), rabbit DEFB113 (61% identical), mouse Defb18 (54% identical), rat Defb18 (50% identical).
Diseases named in the same sentence as DEFB113 in open-access papers:
DEFB113 is named in the same sentence as 1 disease in open-access papers, as found by Europe PMC text mining. Sharing a sentence is not in itself a finding about the gene and the disease.
DEFB113 shares sentences with these, for which no sentence is quoted: fungal infections (1 paper).